IL11 (interleukin 11)
Diseases named in the same sentence as IL11 in open-access papers (continued):
Sharing a sentence is not in itself a finding about the gene and the disease.
liver cancer (7 papers, 2011 to 2021). An epithelial or non-epithelial malignant neoplasm that arises from the liver. "In contrast, some studies have shown that YTHDF2 could inhibit the progression of liver cancer by stabilizing EGFR or IL-11 mRNA." (PMID 33519919, 2020). "The expression of 5 TGFβ-responsive genes (IL11, SERPINE1, SMAD7, SNAI1 and TGFBI) was further validated in other liver cancer cell lines." (PMID 34571856, 2021). "A prominent example of such a regulatory interaction is found between lncRNA-ATB and IL11 mRNA leading to the stabilization of the latter which results in an activated IL11/STAT3 signalling and enhanced metastatic potential of liver cancer cells." (PMID 32727085, 2020).
multiple sclerosis (7 papers, 2012 to 2023). A progressive autoimmune disorder affecting the central nervous system resulting in demyelination. "Critical pathological roles for dysregulated IL-11 have been identified in autoimmune diseases including arthritis, asthma, inflammatory bowel disease, multiple sclerosis, and systemic sclerosis." (PMID 37985757, 2023). "Inhibition of IL-11 signalling has been shown to provide therapeutic benefit in models of arthritis, multiple sclerosis, neointimal hyperplasia, multiple fibrotic diseases, and gastrointestinal cancers." (PMID 37985757, 2023). "Another recent publication indicates that IL-11 is also a key factor in the development of multiple sclerosis." (PMID 33211714, 2020). "IL-11 has also been shown to play an immunomodulatory role in an experimental autoimmune encephalomyelitis (EAE) model for multiple sclerosis with increased inflammation, demyelination, and oligodendrocyte and neuronal loss in IL-11Rα-deficient mice." (PMID 22715999, 2012). "Another study reported that in multiple sclerosis patients, IL-11 could induce a differentiation of naive CD4+ Th cells into Th17 cells, as well as the expansion of Th17 memory cells." (PMID 30728748, 2019). "IL-11, a newer member of the gp130 family of cytokines, has recently been shown to play an anti-inflammatory and neuroprotective role in multiple sclerosis and a role in mediating oligodendrocyte viability and maturation in enriched primary oligodendrocyte human fetal cultures." (PMID 22715999, 2012). "Moreover, recent studies have shown that IL-11 regulated the autoimmune demyelination disease-multiple sclerosis (MS)." (PMID 22433466, 2012).
non-alcoholic steatohepatitis (7 papers, 2021 to 2025). "IL11 contributes to the development of non-alcoholic steatohepatitis (NASH) through incompletely understood mechanisms." (PMID 33397952, 2021). "Recently, we documented a previously unappreciated role for interleukin-11 (IL11) in the transformation of HSCs into myofibroblasts in the liver, a defining pathology in non-alcoholic steatohepatitis (NASH)." (PMID 35408908, 2022).
Thrombocytosis (7 papers, 2014 to 2025). Increased numbers of platelets in the peripheral blood. "The production of hepatic thrombopoietin and subsequent thrombocytosis is caused by elevated levels of thrombopoietin-inducing cytokines, such as interleukin-1 (IL-1), IL-3, IL-11, and tumor-derived IL-6, in tumor-host tissues." (PMID 39941717, 2025). "Production of thrombopoietic cytokine in liver and thrombocytosis are caused by interleukin-1 (IL-1), IL-3, IL-4, IL-11, and tumor-derived platelet factor 4 in tumor host tissues." (PMID 35268446, 2022). "Inflammatory conditions are a common cause of thrombocytosis and are related to an elevated C-reactive protein or accelerated sedimentation rate as well as elevated pro-inflammatory cytokines such as interleukin-6 (IL-6) and interleukin-11 (IL-11)." (PMID 34945099, 2021). "Although the mechanism of thrombocytosis is not completely understood, accelerated megakaryopoiesis due to elevated megakaryocytic growth factors such as thrombopoietin, interleukin (IL)-6, or IL-11 has been assumed." (PMID 32181630, 2020).
atherosclerosis (6 papers, 2015 to 2023). A disease characterized by the build-up of fatty material and calcium deposition in the arterial wall resulting in partial or complete occlusion of the arterial lumen. "The anti-inflammatory cytokines that were upregulated in AAA at 7, 14, and 28 days include IL-6, Il-2, IL-11, and IL-10; however, the anti-inflammatory cytokines that were upregulated in atherosclerosis include IL-6 and IL-2." (PMID 38327764, 2023). "A possible link of IL11 with coronary artery disease is intriguing given the central role of VSMC phenotypic switching in atherosclerosis and the fact that anti-inflammatory therapies are proving effective in patients with coronary disease." (PMID 33082445, 2020). "We speculate that increased IL-11 might play a cardioprotective role as a reactive response to atherosclerosis in CHD." (PMID 26098632, 2015). "To investigate the impact of IL11 expression on aortic inflammation, we probed for galectin-3 (LGALS3) and lysosome-associated membrane protein-2 (LAMP2) expression which are known markers for macrophages but also rarely expressed in VSMCs in response to atherosclerosis or injury." (PMID 33082445, 2020). "Furthermore, other upregulated genes were those of the pro-inflammatory interleukins IL3RA, IL7R, IL8, IL11, usually secreted by immune system cells, and of the NF-κB family (NF-κBIA, NF-κBIZ, NF-κBIE), nuclear transcription factors known to be involved in the development of atherosclerosis." (PMID 28224128, 2017).
endometriosis (6 papers, 2007 to 2025). The growth of functional endometrial tissue in anatomic sites outside the uterine body. "Decidual cells release cytokines and growth factors that help to regulate processes of appropriate trophoblast invasion, which could be interrupted by changes caused by endometriosis, particularly in IL-11 levels." (PMID 37629431, 2023). "IL-11 expression is reduced in the eutopic endometrium of endometriosis patients compared to controls." (PMID 40072055, 2025). "However, the precise mechanisms linking IL-11 signaling to decidualization in the eutopic endometrium of endometriosis patients require further investigation." (PMID 40072055, 2025). "The enrichment of an IL11+-expressing stromal cell subcluster in the endometriosis ME samples that express many estrogen-responsive, pro-inflammatory, pro-fibrotic, and senescence gene markers provides some support for this possibility, but this needs confirmation in larger datasets." (PMID 36104692, 2022).
Obesity (6 papers, 2020 to 2024). Accumulation of substantial excess body fat. "Thus, systemic deletion of IL-11 causes not only a reduction in bone formation with increased adiposity in the bone marrow, but also an increase in systemic adiposity leading to obesity and insulin resistance." (PMID 36424386, 2022). "In high-fat diet-induced obesity, hepatic inflammation resulting from sustained IL-6 or IL-11 activation leads to steatohepatitis and hepatitis." (PMID 38999780, 2024). "After further analyses of these shared gene-sets, overexpressed pro-inflammatory cytokines and cytokine receptors (e.g., IL11, IL20RA, IL27RA) could be linked to less thermogenic DN adipocytes, and thereby, to obesity and inflammation." (PMID 32316277, 2020).
parasite infection (6 papers, 2013 to 2022). "Furthermore, cytokines, IL-6, IL-10, and IL-11 stimulate humoral immune responses during parasite infection that could cause differences in expression level of immunoglobulins and humoral immune responses in both fish species during PKD pathogenesis." (PMID 25563603, 2015). "In the fish, IL11 is strongly upregulated across tissues in response to viral, bacterial or parasitic infection." (PMID 36012165, 2022). "IL-11 accelerates platelet recovery, which is important to maintain adequate blood volume levels following parasite infection." (PMID 31269896, 2019). "The transcript level of IL-11, an anti-inflammatory cytokine of IL-6 family, was increased following WT parasite infection and decreased following PbMLFK-KO parasite infection." (PMID 27995998, 2016). "Parasitemia was significantly correlated with the markers of thrombopoiesis TPO and IL-11 and with ICAM-1." (PMID 32687542, 2020).
Arthritis (5 papers, 2020 to 2025). Inflammation of a joint. "In an unique early study, endogenous IL11 was shown to be disease-causing in a mouse model of arthritis." (PMID 38054591, 2023). "The IL-6 family cytokines LIF and IL-11 are also implicated in arthritis." (PMID 33374841, 2020). "Of note, opposing effects of rhIL11 and endogenous mouse Il11 had been reported previously in a mouse model of arthritis." (PMID 38054591, 2023).
atrophic gastritis (5 papers, 2013 to 2024). "As proinflammatory cytokines involved in atrophic gastritis, IL-6 and IL-11 cause an inflammatory response in the stomach and play important roles in angiogenesis and cell proliferation during the progression of neoplasia; thus, they are used as biomarkers of aggressive tumors." (PMID 26839577, 2016). "Previously, in a study assessing the effects of maximal gp130/STAT3 activation on the gastric mucosa, we reported that systemically administered IL-11 (20μg/day) caused gastric atrophy and mucus metaplasia through STAT3 activation, and coincident with elevated IL-1β expression." (PMID 25528766, 2015). "In particular, IL-11 expression increases in atrophic gastritis and in intestinal metaplasia of the fundic mucosa." (PMID 26839577, 2016). "This demonstrates that IL-11 can promote gastric atrophy, consistent with our previous findings and that IL-1 signaling antagonizes IL-11-dependent tumorigenesis." (PMID 25528766, 2015). "In particular, IL-11, which is mainly expressed in the fundic mucosa, might play a pivotal role in atrophic gastritis and the progression of GC." (PMID 26839577, 2016).
autoimmune disease (5 papers, 2021 to 2024). A disorder resulting from loss of function or tissue destruction of an organ or multiple organs, arising from humoral or cellular immune responses of the individual to their own tissue constituents. "We combined computational and histological approaches to validate the expression status of IL11 and IL11Rα in human fibrotic and additional autoimmune diseases." (PMID 38455057, 2024). "Previous studies have shown that interleukin (IL)-11 plays a pivotal profibrotic role in various inflammatory and autoimmune diseases." (PMID 35273577, 2022).
Cerebral ischemia (5 papers, 2018 to 2025). Restriction of arterial blood supply to the brain associated with insufficient oxygenation to support the metabolic requirements of the tissue. "In cases of cerebral bleeding and cerebral ischemia, the expression and effect of IL-11 are opposed." (PMID 37304948, 2023). "Conversely, another research revealed that IL-11 mRNA and protein expression reduce considerably after cerebral ischemia." (PMID 37304948, 2023). "A previous research identified a reduction in the IL11 level in the context of cerebral ischemia–reperfusion injury, while administration of IL11 notably mitigated the activation of astrocytes and microglia induced by ischemia and also reduced the production of pro-inflammatory cytokines." (PMID 39886603, 2025). "In addition, many enriched inflammatory markers after cerebral ischemia, including interleukins IL-11 and IL-6, chemokines (Ccl4, Ccl2, Ccl5) and serum amyloid A (Saa3), were observed to be up-regulated consistent with reports elsewhere." (PMID 29896414, 2018). "A recent mouse model restriction of cerebral ischemia-reperfusion injury found that IL-11 was declined in the cerebral ischemia model, and the upregulation of the IL-11 expression could improve the cerebral ischemia neuropathy injury and neurological function score." (PMID 36875689, 2023).
cervical cancer (5 papers, 2021 to 2025). A primary or metastatic malignant neoplasm involving the cervix. "Our results indicate that IL-11 causes the radioresistance of cervical cancer through PI3K/Akt signaling pathway." (PMID 34149927, 2021). "In this research, TCGA databases revealed that IL-11 expression was upregulated in cervical cancer tissues and was associated with clinical stages and poor prognosis in cervical cancer patients." (PMID 34149927, 2021). "Nevertheless, it is still unclear that the exact roles and underlying mechanisms of IL-11 in cervical cancer radioresistance." (PMID 34149927, 2021). "After we detected IL-11 concentrations in the cell supernatants in the cervical cancer cell lines (HeLa, SiHa, CaSki and C33A) and normal cervical epithelial cell lines (Ect1/E6E7) using ELISA analysis." (PMID 34149927, 2021). "Cervical cancer patients in stage II exhibited a higher IL-11 expression than the patients in stage I. However, cervical cancer patients in stage IV exhibited a lower IL-11 expression than the patients in stage I." (PMID 34149927, 2021). "Bioinformatics analysis indicated that IL-11 mRNA was significantly elevated in human cervical cancer tissues compared with normal tissues." (PMID 34149927, 2021). "In the present study, we first determined the expression of IL-11 in the cervical cancer radiosensitive and radioresistant cells." (PMID 34149927, 2021). "In summary, for the first time, we demonstrate that IL-11 is critical for the development of radioresistance in cervical cancer cells." (PMID 34149927, 2021). "In this study, we found that the expression of IL-11 was increased in radioresistant cervical cancer cells compared to radiosensitive cervical cancer cells." (PMID 34149927, 2021). "We discovered that IL-11 concentration was significantly upregulated in radioresistant cervical cancer cells." (PMID 34149927, 2021). "Accordingly, our work revealed that IL-11 participates in radioresistance in cervical cancer through activating the PI3K/Akt signaling pathway." (PMID 34149927, 2021). "Altogether, our results demonstrate that IL-11 might be involved in radioresistance, and IL-11 may be a potent radiosensitization target for cervical cancer therapy." (PMID 34149927, 2021). "Subsequent functional studies confirmed this notion that knockdown of IL-11 could increase the radiosensitivity of radioresistant cervical cancer cells, whereas rhIL-11 enhanced the radioresistance in radioresistant cervical cancer cells." (PMID 34149927, 2021). "To identify whether IL-11 was upregulated in cervical squamous cell carcinoma, we analyzed data from TCGA, which included 305 cervical cancer tissues and 3 normal tissues." (PMID 34149927, 2021). "We further analyzed the expression level of IL-11 in cervical cancer cells." (PMID 34149927, 2021). "Our findings indicate that targeting IL-11 may be a potential strategy to overcome radioresistance in cervical cancer." (PMID 34149927, 2021). "Moreover, we for the first time show that IL-11 influenced radiotherapy tolerance of cervical cancer cells through the PI3K/Akt signaling pathway." (PMID 34149927, 2021). "Nevertheless, the exact roles and underlying mechanisms of IL-11 in cervical cancer radioresistance have not been elucidated yet." (PMID 34149927, 2021). "Our results suggest that IL-11 reduction enhances the radiosensitization of cervical cancer patients may be through inhibiting the PI3K/Akt signaling pathway." (PMID 34149927, 2021). "Our findings suggested that targeting IL-11 might be a promising therapeutic option for the treatment of radioresistance in cervical cancer patients." (PMID 34149927, 2021). "To analyze whether IL-11 can affect the radiosensitivity of cervical cancer cell lines, we inhibited IL-11 by independent shRNAs." (PMID 34149927, 2021). "Our studies demonstrated that IL-11 is overexpressed in radioresistant cervical cancer cells, indicating that IL-11 may be involved in the radiosensitivity of cervical cancer." (PMID 34149927, 2021).
cervical cancer (continued). "Secondly, we investigated the function of IL-11 in radioresponse of cervical cancer cells." (PMID 34149927, 2021). "Given that IL-11 is overexpressed and promotes radioresistance in cervical cancer, IL-11 might serve as an attractive candidate to predict radiosensitivity and is a potential therapeutic target for cervical cancer." (PMID 34149927, 2021). "IL-11 concentration was up-regulated in cervical cancer cells (HeLa, SiHa, CaSki and C33A) contrasting with the normal cervical epithelial cell lines (Ect1/E6E7)." (PMID 34149927, 2021). "However, the exact effects and mechanisms of IL-11 in the radioresistance of cervical cancer have not yet been defined." (PMID 34149927, 2021).
chronic kidney disease (5 papers, 2022 to 2025). Impairment of the renal function secondary to chronic kidney damage persisting for three or more months. "In mouse models of AKI or accelerated chronic kidney disease, administration of anti-IL11 is associated with lesser renal pathology and improved renal function." (PMID 36470928, 2022). "Notably, it was discovered that over-expression of IL11 is associated with chronic kidney disease and correlates positively with low GFR and elevated serum creatine levels, indicating that IL11 could potentially have a detrimental impact on kidney function." (PMID 37480086, 2023). "IL11 expression was found to be over-expressed in chronic kidney disease with tubulointerstitial fibrosis and tubular cell damage, compared to normal kidney, in the Nakagawa CKD Kidney in Nephroseq v5 database." (PMID 37480086, 2023). "To examine the role of IL11 in a model of accelerated chronic kidney disease, we performed a separate set of experiments using the unilateral ureteral obstruction (UUO) model and first determined if IL11 was upregulated." (PMID 36470928, 2022). "Our studies suggest potential therapeutic opportunities for anti-IL11 in acute and chronic kidney diseases." (PMID 36470928, 2022). "In a model of chronic kidney disease, anti-IL11 therapy promotes TEC proliferation and parenchymal regeneration, reverses fibroinflammation and restores renal mass and function." (PMID 36470928, 2022). "Additionally, targeting endogenous kidney regeneration using anti-IL-11 therapy has been demonstrated to reduce inflammatory gene expression and improve renal function in both acute and chronic kidney disease models." (PMID 39744177, 2025). "Thus, in the setting of established chronic kidney disease, anti-IL11 is permissive for TEC regeneration, reverses fibrosis and pEMT phenotypes, and improves renal function." (PMID 36470928, 2022). "Moreover, the observation that urinary IL-11 excretion directly correlated with proteinuria in patients with IgA nephropathy and lupus nephritis, raises the possibility that IL-11 signaling may be of relevance also in other proteinuric chronic kidney diseases." (PMID 39529801, 2024). "Notably, IL-11 remains undetected in the serum of healthy individuals due to its predominant regulation of extracellular matrix (ECM) rather than immune responses, favoring alternative ERK activity over JAK/STAT3 activity in chronic kidney disease (CKD) settings." (PMID 38732588, 2024).
depression (5 papers, 2013 to 2022). "Lastly, our study was unable to evaluate some immune markers and cytokines previously linked to WNV infection such as IL-2, IL-4, IFN-B, TLR-3, IL-11, and IL-18, as well as some previously linked to depression such as IL-18 and NFκB." (PMID 35745504, 2022). "Results from the Genome-based Therapeutic Drugs for Depression Project (GENDEP) identified a single nucleotide polymorphism (SNP) in the cytokine IL11 gene that predicted response to escitalopram." (PMID 32012861, 2020).